THBS2 (thrombospondin 2)
Diseases named in the same sentence as THBS2 in open-access papers (continued):
Sharing a sentence is not in itself a finding about the gene and the disease.
gastric adenocarcinoma (3 papers, 2022). "We also investigated the impact of CAF markers highly clustered with COL1A1 and COL5A1 in correlation analysis, namely THBS2, FAP, INHBA, S100A4, COL11A1, or MMP11, on the outcome of CAF infiltration in stomach adenocarcinoma." (PMID 35739492, 2022). "Moreover, THBS2 may function as a bridge between the ECM and immune infiltration in cancer and serve as a potential prognostic biomarker for several cancers, especially pancreatic and gastric adenocarcinomas." (PMID 35701829, 2022).
malaria (3 papers, 2018 to 2023). Malaria is a serious and sometimes fatal disease caused by a parasite that commonly infects a certain type of mosquito which feeds on humans. "Pathway enrichment analysis revealed that THBS2 is significantly regulated following signaling pathways: ECM-receptor interaction, malaria, leukocyte transendothelial migration, phagosome, focal adhesion, and proteoglycans in cancer." (PMID 38162289, 2023). "Within the malaria pathway, miR-193b promotes the THBS1, THBS2, and TGFβ2 genes; and regulates apoptosis by targeting myeloid leukaemia cell differentiation protein 1, among others." (PMID 29747626, 2018).
myeloma (3 papers, 2014 to 2022). "It has recently been demonstrated that the forced expression of HOXB7 in multiple myeloma induces the up-regulation of VEGFA, FGF2, MMP2 and PDGFA, and the down-regulation of thrombospondin 2, a profile largely shared by RC." (PMID 25115389, 2014).
squamous cell carcinoma (3 papers, 2016 to 2021). A carcinoma arising from squamous epithelial cells. "In contrast, overexpression of THBS2 suppressed tumor growth in squamous cell carcinomas and Lewis lung carcinoma xenograft mouse tumor models." (PMID 27513329, 2016). "Moreover, THBS2 was also observed with significantly higher level in two main histological types of NSCLC of AC (P<0.001) and squamous cell carcinoma (SC, P<0.0001) than that in healthy control subjects." (PMID 31296790, 2019).
triple-negative breast carcinoma (3 papers, 2022 to 2025). An invasive breast carcinoma which is negative for expression of estrogen receptor (ER), progesterone receptor (PR), and human epidermal growth factor receptor 2 (HER2). "Thrombospondin-2 (THBS2) is a prevailing prognostic biomarker implicated in different cancer types, such as deadly colorectal, pancreas, and triple-negative breast cancers." (PMID 40141965, 2025). "THBS2 might serve as a promising functional biomarker for patients with triple-negative breast cancer." (PMID 36405394, 2022). "THBS2 might serve as a promising functional predictive and prognostic biomarker for patients with triple-negative breast cancer." (PMID 36405394, 2022).
urothelial carcinoma (3 papers, 2021 to 2024). A malignant neoplasm derived from the transitional epithelium of the urinary tract (urinary bladder, ureter, urethra, or renal pelvis). "In urothelial carcinomas, THBS2 high expression was significantly associated with nodal metastasis and vascular invasion." (PMID 34804159, 2021).
acute respiratory distress syndrome (2 papers, 2023). Progressive and life-threatening pulmonary distress in the absence of an underlying pulmonary condition, usually following major trauma or surgery. "THBS2 overexpression can effectively inhibit LPS-induced acute respiratory distress syndrome in vivo and promote macrophage polarization to M2 phenotype in vitro." (PMID 37055866, 2023).
adenoma (2 papers, 2015 to 2022). A neoplasm arising from the epithelium. "No significant gene expression alterations could be detected in the stromal cells isolated from adenomas compared to the normals, but COL1A2, FADS1, MAL, PRIMA1, SULF1, THBS2, TIMP1 genes’ transcripts showed significant differences (p < 0.05) in logFc values for the tumour versus normal comparison." (PMID 26482433, 2015). "In addition, ALDH1A3, COL1A2, FADS1, SFRP2, SULF1, and THBS2 were found to be significantly (p < 0.01) differentially expressed in tumour samples but not in adenomas compared to healthy samples." (PMID 26482433, 2015).
Alzheimer disease (2 papers, 2023 to 2025). A progressive, neurodegenerative disease characterized by loss of function and death of nerve cells in several areas of the brain leading to loss of cognitive function such as memory and language. "For instance, Cluster 8 was associated with relatively lower DCDQ scores than those of other clusters but higher SCQ and RBS-R scores, with genes such as THBS2, WDR27, and ORF13F1 being associated with Alzheimer’s disease." (PMID 40440618, 2025).
aortic valve calcification disease (2 papers, 2022 to 2024). "Previous studies have found that THBS2, COL1A1, and LUM are closely related to aortic valve calcification disease." (PMID 39749331, 2024). "Thrombospondin 2 (THBS2) is reported to participate in the development of calcific aortic valve disease (CAVD), while the effects are not elucidated completely." (PMID 36118676, 2022).
atrial fibrillation (2 papers, 2022 to 2025). A disorder characterized by an electrocardiographic finding of a supraventricular arrhythmia characterized by the replacement of consistent P waves by rapid oscillations or fibrillatory waves that vary in size, shape and timing and are accompanied by an irregular ventricular response. "At the RNA level, RT-qPCR confirmed expression changes in CACNG4 (cardiac arrythmia), GJA5 (atrial fibrillation), THBS2 (angiogenesis inhibitor), ADD2 (membrane skeletal protein, synaptic plasticity), and HAND2 (neurogenesis)." (PMID 39508990, 2025).
Atrophy (2 papers, 2015 to 2021). Any weakening or degeneration, especially through lack of use. "Furthermore, anti-angiogenic regulators such as Angiomotin like 2 (Amotl2) and Thrombospondin 2 (Thbs2) were highly expressed in the atrophy group at day 7 and slightly higher at day 42 compared to the control group." (PMID 25910190, 2015). "Here we show that Thbs1, but not Thbs2, Thbs3 or Thbs4, induces lethal cardiac atrophy when overexpressed." (PMID 34168130, 2021).
brain tumor (2 papers, 2022 to 2024). "we have reported five co-regulated clusters via seven important co-expression genes (COL1A2, LUM, SPARC, THBS2, IL1B, CXCL8, THY1) interacting between five clusters of the brain tumours." (PMID 35045088, 2022). "In addition to VEGF, HIF-1α, angiopoietin 1 and 2, and basic fibroblast growth factor (bFGF), the main regulators of angiogenesis in health and in brain tumors are plasminogen activation inhibitor 1 (PAI1), nitric oxide, cyclooxygenase 2 (COX2), and thrombospondin 2 (TSP2)." (PMID 38994941, 2024).
colorectal adenocarcinoma (2 papers, 2019 to 2025). The most common type of colorectal carcinoma. "The TIMER 2.0 database shows a positive correlation between PTN, THBS2, and COL1A2 expression and immune cell infiltration in CAFs of colorectal adenocarcinoma (COAD) and rectal adenocarcinoma (READ)." (PMID 40242441, 2025).
endometrial adenocarcinoma (2 papers, 2015 to 2017). "These high THBS2 promoter methylated in blood were reported in the recurrent endometrial adenocarcinoma patients and THBS2 had methylation in the primary tumor as well." (PMID 29190912, 2017).
Hyperglycemia (2 papers, 2021 to 2022). An increased concentration of glucose in the blood. "In addition, hyperglycemia induces the hexosamine pathway, and NF-κB signaling increases the expression of thrombospondin 2 (TSP2)." (PMID 33628388, 2021).
intraductal papillary mucinous neoplasms (2 papers, 2021). "THBS2, a biomarker previously considered in patients with PDAC, was also associated with intraductal papillary mucinous neoplasms (IPMN) dysplasia." (PMID 34707986, 2021).
invasive breast carcinoma (2 papers, 2018 to 2022). A carcinoma that infiltrates the breast parenchyma. "Gene expression analysis between ductal carcinoma in situ (DCIS) and invasive breast carcinoma (IBC) tissues has indicated that the THBS2 gene is up-regulated during the transition between non-invasive to invasive breast cancer." (PMID 35045088, 2022).
kidney cancer (2 papers, 2022 to 2024). Primary or metastatic malignant neoplasm involving the kidney. "THBS2 and THBS5 presented significantly different between tumor and normal samples in nearly all cancer types, with THBS2 being significantly higher in kidney cancers and brain cancers compared to normal tissues, while THBS5 exhibited the opposite trend." (PMID 39732719, 2024).
lumbar disc herniation (2 papers, 2013 to 2022). "A further example of the combined effect of two unlinked SNPs is provided by an intronic SNP in the thrombospondin 2 (THBS2) gene (c.1478-8C>T; rs 9406328) and a missense SNP in the metalloproteinase 9 (MMP9) gene (Gln279Arg; rs17576), which together increase the risk of lumbar disc herniation." (PMID 23820649, 2013).
Myocardial fibrosis (2 papers, 2019 to 2024). "Thrombospondin-2 appears to be a good therapeutic candidate for prevention of adverse remodeling, which has previously been implicated through gene expression microarrays of murine HF models as a regulator of myocardial fibrosis, repair, and MMPs19,42–44." (PMID 31862877, 2019). "Like SPON2, preclinical studies implicate myocardial THBS2 expression in protection from myocardial fibrosis and dysfunction with aging or in response to hypertension." (PMID 38225249, 2024). "Similar to SPON2 and THBS2, in pre-clinical models, myocardial MFAP4 expression appears to protect from myocardial fibrosis and hypertrophy in response to pressure overload or neurohormonal activation." (PMID 38225249, 2024).
neuroblastoma (2 papers, 2009 to 2018). Neuroblastoma (NB) is the most common solid, extracranial childhood tumor. "Alternatively, neuroblastoma contain low level of PML I and PML I-induced expression of thrombospondin-2 (TSP2), a potent angiogenic inhibitor." (PMID 29416846, 2018).
pancreatitis (2 papers, 2018 to 2025). Inflammation of the pancreas. "We demonstrate that the concentrations of ALPPL2+ and THBS2+ exosomes are significantly elevated in the serum samples of patients with PDAC compared to healthy controls and to patients with non-cancerous conditions such as pancreatitis and cystic lesions." (PMID 40897818, 2025).
proliferative diabetic retinopathy (2 papers, 2015). Advanced retinopathy due to diabetes mellitus characterized by the formation of new vessels in the retina. "This is somewhat different from another report showing the overexpression of THBS2 in the vitreous body from patients with proliferative diabetic retinopathy." (PMID 27446820, 2015).
scleroderma (2 papers, 2013 to 2022). Scleroderma is a rare autoimmune connective tissue disorder characterized by abnormal hardening of the skin and, sometimes, other organs. "Furthermore, increased levels of THBS2 have been observed in the blood of patients with scleroderma, suggesting the involvement of THBS2 with inflammation, vascular damage, and fibrosis of the skin and internal organs." (PMID 36506087, 2022).
skin cancer (2 papers, 2016 to 2019). "In contrast, THBS2 was reported to be markedly up-regulated in the tumor microenvironment of skin cancer patients and to have antiangiogenic effects." (PMID 27513329, 2016).
Acidosis (1 paper, 2022). Abnormal acid accumulation or depletion of base. "Additionally, the top seven nodes of the “Acidosis” network were present among the top ten nodes of “Acidosis and Bone metastasis”: COL1A1, COL3A1, COL4A1, COL4A2, ITGB3, THBS2, and ITGA11." (PMID 35159353, 2022).
Anxiety (1 paper, 2022). Intense feelings of nervousness, tension, or panic often arise in response to interpersonal stresses. "Furthermore, changes in CTCF looping around genes such as Adcyap1 and Thbs2 are associated with sex- and oestrous cycle-dependent gene expression differences and further provide a possible link between 3D genome changes and anxiety-related behavioural phenotypes." (PMID 35705546, 2022).
autoimmune pancreatitis (1 paper, 2022). "Three of five patients with autoimmune pancreatitis patients had greatly elevated thrombospondin-2 levels." (PMID 34319497, 2022). "However, elevated THBS2 levels in the BDs were diagnosis- and cutoff- dependent, with autoimmune pancreatitis showing substantially elevated THBS2 levels." (PMID 34319497, 2022).
Burkitt lymphoma (1 paper, 2022). A rare form of malignant mature B-cell non-Hodgkin lymphoma. "Analysing gene expression data of Burkitt lymphoma transcriptome sequencing from African patients revealed six biomarkers (ADAMTSL4, SEMA5B, ADAMTS15, THBS2, SPON1 and THBS1) as possible indicators for diagnostic and prognostic targets towards BL management." (PMID 36354023, 2022).
Cerebral ischemia (1 paper, 2023). Restriction of arterial blood supply to the brain associated with insufficient oxygenation to support the metabolic requirements of the tissue. "After cerebral ischemia, thrombospondin 2 (TSP2) is highly upregulated during the sub-acute phase, while thrombospondin 1 (TSP1) shows a more transient and earlier upregulation." (PMID 39086680, 2023).
Charcot-Marie-Tooth disease (1 paper, 2017). An inherited degenerative disorder involving the peripheral nerves. "Four genes were identified with alterations in more than one family include PLEKHG5, a gene that causes Charcot-Marie-Tooth disease and THBS2, which promotes synaptogenesis." (PMID 29177109, 2017).
chordoma (1 paper, 2015). Chordomas are rare malignant tumors arising from embryonic remnants of the notochord in axial skeleton. "In the exophytic chordoma tissues, the expression of tumor cell motility-associated proteins such as TGFβ1, HGDF, THBS2 and FBLN5 were significantly higher than that of the endophytic type." (PMID 25793716, 2015).
chronic myeloid leukemia (1 paper, 2016). "The significantly enriched pathways included chemokine signaling pathway (which involved CCL2), focal adhesion (which involved THBS1 and THBS2), TGF-beta signaling pathway (which involved THBS1, THBS2, SMAD5, and SMAD6) and chronic myeloid leukemia (which involved TGFBR2 and CCND1)." (PMID 27716259, 2016).
craniosynostosis (1 paper, 2011). Craniosynostosis is defined as the premature fusion of one or more cranial sutures leading to secondary distortion of skull shape resulting in skull deformities with a variable presentation. "In another study comparing differential expression during suture fusion from a mix of syndromic and nonsyndromic craniosynostosis cases, THBS2 and collagen types 2, 3, 4, 6, 8, 10 and 11 were found to be upregulated in unfused sutures." (PMID 22028906, 2011). "Upregulation THBS2 and collagen types 6 and 11 were observed in this study as well, alluding to the fact that cartilage-specific gene expression and perturbations to ECM-mediated processes are involved in suture morphogenesis and a common feature in all forms of craniosynostosis." (PMID 22028906, 2011).
glioblastoma (1 paper, 2022). The most malignant astrocytic tumor (WHO grade IV). "TGFβ1 induces THBS1 (thrombospondin-1) expression via Smad3, which contributes to invasive behavior during glioblastoma expansion; TGF-β also stimulates both THBS1 and CISP/THBS2 synthesis by bovine adrenocortical cells." (PMID 36535930, 2022).
ischemic cardiomyopathy (1 paper, 2023). Ischemic cardiomyopathy is a cardiomyopathy in which a weakness in the muscle of the heart due to inadequate oxygen delivery to the myocardium with coronary artery disease being the most common cause. "There are two emerging biomarkers for ischemic cardiomyopathy: angiopoietin-2 and thrombospondin-2, that are now used in addition to BNP and cardiac troponin." (PMID 37210547, 2023).
mesothelioma (1 paper, 2022). A usually malignant and aggressive neoplasm of the mesothelium which is often associated with exposure to asbestos. "High THBS2 expression was an independent unfavorable prognostic factor in kidney renal papillary cell, mesothelioma, and stomach and pancreatic adenocarcinomas." (PMID 35701829, 2022).
metastatic cancer (1 paper, 2022). A carcinoma which has spread from the original site of growth to another anatomic site. "There are five genes (BGN, THBS2, SPARC, CDH11 and SPP1) in metastatic cancer tissues that are significantly higher than non‐metastatic cancer tissue at the transcriptomics level, while only BGN and THBS2 were significant difference in protein expression between metastatic and non‐metastatic cases." (PMID 36377223, 2022).
metastatic prostate carcinoma (1 paper, 2013). A carcinoma that arises from the prostate gland and has spread to other anatomic sites. "Thrombospondin-2, a modulator of angiogenesis, has also been reported to be differentially expressed when comparing non-metastatic and metastatic prostate cancer samples in two independent studies." (PMID 23826159, 2013).
mucinous ovarian carcinomas (1 paper, 2022). An invasive malignant neoplasm that arises from the ovary and is characterized by the presence of malignant epithelial cells that contain intracytoplasmic mucin and may resemble the epithelial cells of the endocervix or gastrointestinal tract. "This analysis of a large series of mucinous ovarian carcinomas has identified two potential prognostic biomarkers in THBS2 and TAGLN, which could have clinical utility and deserve further investigation." (PMID 36222710, 2022).
ovulation (1 paper, 2023). The release of a mature ovum/oocyte from an ovary. "Compared to the single model, the combined model of clinical (Ovulation dysfunction) and specific genes (GAST, GPX3, THBS2) was more accurate to predict live birth for IVF-ET patients." (PMID 37777726, 2023).
peripheral nerve injury (1 paper, 2018). Injury to a peripheral nerve. "Based on our findings, GPNMB, ENPP3, Thbs2, and Lgals3 may play a key role in repair of SCs after peripheral nerve injury." (PMID 30186571, 2018).
polycystic ovary syndrome (1 paper, 2013). A disorder that manifests as multiple cysts on the ovaries. "In the recurrence subnetworks, DCN, THBS1, and THBS2 are members of the signaling KEGG pathway, and FBN1 controls the bioactivity of TGFs and relates to polycystic ovary syndrome." (PMID 23555212, 2013).
prostate adenocarcinoma (1 paper, 2021). "Here, we found downregulated methylation of THBS1 in BRCA, THBS2 in KIRC, and THBS4 in PRAD (prostate adenocarcinoma) and LIHC (liver hepatocellular carcinoma)." (PMID 34804159, 2021).
pulmonary artery hypertension (1 paper, 2023). "Repression of Thbs2 greatly contributes to the reduction of fibrosis in the context of pulmonary artery hypertension-induced cardiac injury, indicating the antifibrotic potential of Thbs2." (PMID 37667335, 2023).
rectal cancer (1 paper, 2022). A primary or metastatic malignant neoplasm that affects the rectum. "Lower THBS2 expression was linked to advanced disease status and slower tumour regression after preoperative neoadjuvant concurrent chemoradiotherapy, THBS2 acted as an independent negative prognostic factor in rectal cancer." (PMID 36377223, 2022).
renal cell carcinoma (1 paper, 2024). "Another study on renal cell carcinoma (RCC) revealed a different pathway, where IGF2BP3 stabilizes AGAP2-AS1, allowing it to competitively bind with miR-9-5p, consequently upregulating the expression of Thrombospondin-2 (THBS2) and activating the PI3K/AKT signaling pathway." (PMID 39521940, 2024).
round cell liposarcoma (1 paper, 2017). A poorly differentiated liposarcoma, characterized by the presence of solid sheets of primitive round mesenchymal cells and the absence of myxoid stroma. "MiR-135b exerts its tumor promoting role in myxoid/round cell liposarcoma by supporting cell invasion and metastasis through suppressing thrombospondin 2 (THBS2)." (PMID 28036291, 2017).
skin aging (1 paper, 2023). The gradual irreversible changes in structure of skin that occur as a result of the passage of time.. "Then, we confirmed the down-regulated expressions of ABCC4, PTGER3, BCEH, HPGD, and MOXD1 in normal group, while AR, CXCR2, HSD17B2, ODC1, PI3, PLAU and THBS2 were up-regulated in skin aging group." (PMID 37310405, 2023).